CLDN4 (claudin 4)
Diseases named in the same sentence as CLDN4 in open-access papers (continued):
Sharing a sentence is not in itself a finding about the gene and the disease.
cancer (continued). "To validate the cell specific expression, we performed RNA in situ hybridization for Claudin-4 and FAP-α, which were, as expected, seen in the SW480 cancer cells and the 1BR.3.G fibroblasts, respectively." (PMID 39011470, 2024). "Claudin-2 (CLDN-2) and claudin-4 (CLDN-4) are leaky-type tight junction proteins, and their overexpression increases the tumorigenesis of some types of cancer cells." (PMID 38338691, 2024). "Notably, the multifocal expression of CAM5.2 and claudin-4, with a predominance of epithelioid cells, lent support to the hypothesis of an epithelial lineage, ultimately leading to the classification as metastatic poorly differentiated epithelial carcinoma." (PMID 39329865, 2024). "Cancers with MSI were characterized by downregulation of claudin 1, claudin 3, and claudin 4 and upregulation of claudin 7 and occludin." (PMID 37998722, 2023). "No connections of these clusters with GRHL2 were visible but the interaction of GRHL2 with CLDN4 was shown as well as co-expression of GRHL2 with TACSTD2, a transmembrane receptor regulating cell proliferation and migration in development and cancer." (PMID 36691073, 2023). "We observed that CLDN3, CLDN4, and CLDN7 transcripts were up-regulated in most of the dysplastic or cancer cells, although these genes were also expressed in some of the intestinal cell lineages." (PMID 37196797, 2023). "Recently, single‐cell analysis of the transcriptome and epigenome also showed that KRT8, KRT18, CLDN4, KRT19, KRT20, etc. are highly expressed in CRCs,[12a] consistent with our results that these genes were highly expressed in cancer EPCs." (PMID 33898197, 2021). "Affected genes included FGFR1, IRS1, CLDN4, GRB7, and VCAN, while EZR and MYC were commonly affected in at least four out of five progression stages of the selected cancer levels." (PMID 34069906, 2021). "However, the upstream regulator of CLDN4 in cancers remains unknown." (PMID 33006362, 2020). "Clostridium perfringens enterotoxin (CPE) can be used to eliminate carcinoma cells that overexpress on their cell surface CPE receptors – a subset of claudins (e.g., Cldn3 and Cldn4)." (PMID 31825142, 2020). "Considerable efforts have been made to understand the role of claudin-4 in the development of PDAC and a variety of other cancer types." (PMID 28842811, 2018). "CD24 has prognostic value in survival as a marker for cancer stem cells whereas CLDN3 and CLDN4 have been shown to regulate the epithelial to mesenchymal transition." (PMID 30383866, 2018). "When CLDN1, CLDN4, and CLDN18 were analyzed throughout the 18 cancer types as a multi-marker set, the AUC value was 0.850 (p=3.3×10-4)." (PMID 29050243, 2017). "When CLDN1, CLDN4, and CLDN18 were analyzed, as single markers, across 18 cancer tissue types, the AUC values were 0.756 (p=1.4×10-4), 0.647 (p=0.156), and 0.792 (p=2.5×10-4), respectively." (PMID 29050243, 2017). "Particularly, due to the critical role of CLDN4 in the formation of tight junctions, disruption and dysfunction of tight junctions originating from the aberrant expression of CLDN4 may decrease the stability of cell-to-cell adhesions and thus facilitate the detachment and metastasis of cancer cells." (PMID 28819095, 2017). "Furthermore, previous studies reported that claudin-4 may have potential as a treatment for cancer." (PMID 23822740, 2013). "Membranous staining for claudin-4 and PSMA was also observed in luminal cells of HG-PIN and in carcinoma cells." (PMID 18648369, 2008). "These cancers are thus ideal candidates for a for a novel therapy being developed based on CPE, a toxin that specifically binds claudin-3 and claudin-4." (PMID 16836752, 2006). "Carcinoma markers, such as claudin-4, MOC-31, and Ber-EP4 are not usually helpful in the differential diagnosis, so they should not be included in the panel." (PMID 39941848, 2025).
cancer (continued). "Claudin-4 is aberrantly expressed in most epithelial ovarian carcinomas, and in up to 75% of HGSOC tumors, where it functions as a driver in the development of resistance to cancer therapeutics, ultimately leading to worse patient outcomes." (PMID 38867360, 2024). "Therefore, it is recommended to use panels consisting of at least two carcinoma markers (such as pCEA BER-EP4, MOC-31, Claudin 4, HEG1) and two mesothelial markers (such as WT1, calretinin, CK5/6, D2-40)." (PMID 39407894, 2024). "We analyzed claudin-4, since previous reports had shown that it is more abundant in MDCK cells, stably expressing E7 oncoprotein from human papillomavirus 16, and displays an altered pattern of expression in a wide variety of carcinomas." (PMID 38473701, 2024). "On the other hand, CMS1 cancers, which possessed the highest prevalence of BRAF mutations, presented a downregulated expression of claudin 4 mRNA, independently of the presence or absence of BRAF mutations (two-tailed t test p > 0.05, right)." (PMID 37998722, 2023). "CLDN4 is not exposed in normal cells, but becomes accessible in cancer cells, in which tight junctions are weakened." (PMID 37237291, 2023). "Our expanding knowledge of the functions of TJs and elucidation of the role of non-TJ CLDN4 has revealed the variety of CLDN4 functions and increased awareness of its importance in cancer." (PMID 36982569, 2023). "Non-TJ CLDN4 binds to integrin β1 and enhances stemness, anti-apoptotic effects, drug resistance, and metastatic capacity of cancer cells." (PMID 36982569, 2023). "Claudin-4, a transmembrane tight junction and cell adhesion protein expressed in the normal epithelium and the majority of carcinomas, is not present in normal and neoplastic mesothelial cells." (PMID 36673059, 2023). "In our previous report, CLDN4 overexpression increased malignancy by promoting resistance to anticancer drugs; however, our results show that CLDN4 overexpression increases cancer malignant phenotypes in situations without usage of anticancer drugs." (PMID 35742959, 2022). "Therefore, a combination of the positive and negative markers, including at least two mesothelial cell markers (D2-40, calretinin, WT1) and two cancer cell markers (TTF-1, CEA, polyclonal, claudin-4), is recommended for the diagnosis of DMPM." (PMID 36684194, 2022). "More importantly, the mechanism of nuclear translocation is still not unclear, it is worthy to further reveal how CLDN4 dynamically regulates the early to late stages of cancer." (PMID 35418179, 2022). "Nuclear CLDN4-positive cases showed a stronger correlation with cancer progression than the negative cases." (PMID 32064037, 2020). "Additionally, we verified an immunophenotype comparable to human patient OSPC samples based on the expression of Claudin 3, Claudin 4, Cytokeratin 7, p16, and EMA in SCID pig carcinomas." (PMID 30723704, 2019). "It has previously been reported that claudin-4 is expressed only in cancer, whereas it is not expressed in the normal foveolar epithelium." (PMID 24765156, 2014). "C-CPE-ETA' was strongly cytotoxic towards CLDN-4-positive cancer cell, as opposed to cells lacking CLDN-4 expression." (PMID 22737166, 2012). "In contrast, only one of 50 samples from individuals without cancer exhibited claudin-4-positive exosomes." (PMID 19619303, 2009). "Cancer patient information, CA125 values, and claudin-4 positivity." (PMID 19619303, 2009). "In the mouse model dataset, TPCS cancer cells overexpress the luminal markers Xbp1 and Fgfr3 as well as the basal stem cell markers Itga6 and Cd44, the basal marker Egfr, and the EMT‐related marker Cldn4, suggesting that TPCS are of potential to generate multiple lineages." (PMID 38582099, 2024). "For instance, an LXR inverse agonist is effective against various types of cancer without obvious side effects; therefore, it should be determined whether the LXRβ-targeting treatment could be a therapeutic option in the "CLDN4-high/LXRβ-high" TNBC cases." (PMID 37059993, 2023).
cancer (continued). "This down-regulation was due to transcriptional or post-transcriptional deregulation, given that these cancers did not possess deep deletions or mutations in claudin genes, CLDN3, CLDN4 or CLDN7, and only 5% of claudin-low cases had deep deletions in the occludin gene OCLN." (PMID 37504297, 2023). "To provide further evidence that the loss of E-cadherin and the gain of N-cadherin and Twist expression occurred as a direct result of the claudin status, we examined the effect of expressing CLDN3 and CLDN4 in the human cancer cell line HEY that does not express endogenous CLDN3 or CLDN4." (PMID 23805314, 2013). "Thus, the results suggest that CLDN4 promoter DNA hypomethylation is the cause of CLDN4 overexpression in BUC, and that overexpression results in increased non-tight junction CLDN4, which promotes cancer stemness through integrin β1 activation and consequent increased malignant potential." (PMID 35742959, 2022). "AP-1-clustered sites are present only in the promoter of claudin 4, but the mRNA of this claudin is not upregulated in CMS3 or CMS1 cancers where the KRAS/MAPK pathway is mostly activated due to activating KRAS and BRAF mutations, respectively." (PMID 37998722, 2023). "To investigate targeting of liposomes to cell surface-expressed CLDN4 in vitro, we assessed the cytotoxicity of D@C-LPs in three different cancer cell lines that differentially express CLDN4: ASPC-1 and KPC960 cells, which express CLDN4, and A549 cells, which are negative for CLDN4 expression." (PMID 37237291, 2023). "The recombinant C-CPE-ETA' fusion protein was shown to retain the specificity of binding to CLDN-4 and initiate rapid penetration into cytosol in five different CLDN-4-positive cancer cells (MCF7, A431, SW480, PC3, and DU145) but not to CLDN-4-negative cells (HELA, HUVEC)." (PMID 22737166, 2012). "After incubating cancer cells with D@LPs or D@C-LPs for 4 h, the fluorescence intensity of CLDN4-positive ASPC-1 and KPC960 cells was higher with D@C-LP treatment than with D@LP treatment, whereas the fluorescence intensity of CLDN4-negative A549 cells was similar with D@C-LP and D@-LP treatment." (PMID 37237291, 2023).
infection (32 papers, 2010 to 2025). The state of being infected such as from the introduction of a foreign agent such as serum, vaccine, antigenic substance or organism. "Changes in CLDN4 expression have been associated with epigenetic factors (such as hypomethylation of promoter DNA), inflammation associated with infection and cytokines, and growth factor signaling." (PMID 36982569, 2023). "MNV infection significantly reduced gene expression of claudin 4 and 8 in the proximal colon of 12 week old ASF-associated B6-Il10−/− mice." (PMID 31396223, 2019). "The results of the present study indicate that cell infection with P. gingivalis promoted the expression of the TJ genes encoding occludin, claudin-1 and claudin-4, which enhances barrier function and decreases cell-cell permeability." (PMID 29319048, 2018). "After 24 hours of infection, minor changes in expression were noted, including an increased expression of claudin-4, which is present in the tight junctions of umbrella cells." (PMID 40766562, 2025). "The data revealed that in PAM cells (excluding PAM-4), the viral copy number of PRRSV peaked at 24 h post-infection (hpi), coinciding with the lowest expression levels of CLDN4." (PMID 39875947, 2025). "In fact, infection with the protozoan parasite Cryptosporidium parvum results in a substantial downregulation of CLDN4 in mouse." (PMID 41408150, 2025). "In this study, we observed the elevated levels of both claudin-4 and occludin during infection with CagA+H. pylori strains." (PMID 41341493, 2025). "The similar expression trends of the genes were observed, as EgPSC infection upregulated the mRNA levels of Cldn8, and downregulated the mRNA levels of Pklr, Cldn4 and Cxcl12." (PMID 36713407, 2022). "For example, several classic tight junction related genes (Ocln and Cldn4) were significantly downregulated post-infection, whereas other tight junctions-relative genes (Cldn8, Epb41L2, Prkcb, and Shroom3) were upregulated." (PMID 36713407, 2022). "During the study of the Ct developmental cycle by confocal microscopy, an interesting effect was noticed regarding the expression of the tight junction protein CLDN-4 over the course of the Ct infection." (PMID 34684219, 2021). "In contrast, SCBN incubation with PA (0.3 mM) prior to infection resulted in a significant reduction of ZO-1, claudin-1 and claudin-4 expression compared to control cells exposed to PA (0.3 mM) alone (n = 4)." (PMID 34552170, 2021). "Similar to this, we previously observed a subcellular redistribution of the TJ proteins occludin, claudin-4 and claudin-5 as well as a disorganization of E-cadherin and F-actin in colonic mucosae from pigs infected with E. coli 536 at 5 h after infection." (PMID 34437391, 2021). "Fluorescence microscopy revealed that infection of the epithelial monolayer with C. jejuni results in disruption of pericellular claudin-4, while Western blotting showed significantly less total claudin-4." (PMID 33364202, 2020). "Treatment with curcumin and inhibitors of HDACs, or infection with RSV prevented expression of p63 with an increase of claudin-4 and the number of microvilli." (PMID 28883651, 2017). "We previously reported that OCLN and CLDN-4 were upregulated via NF-κB by infection with RSV in HNECs21." (PMID 28883651, 2017). "The upregulation of claudin-4 and occludin after infection with RSV was enhanced by 1 and 5 μg/ml curcumin and was prevented by 10 μg/ml curcumin." (PMID 24058438, 2013). "In Western blotting, expression of G and M2-1 proteins after infection with RSV was inhibited from 1 μg/ml MG132, and upregulation of phospho-NF-κB, claudin-4 and occludin after infection with RSV was increased at 10 μg/ml MG132." (PMID 24058438, 2013). "In immunocytochemistry, expression of G, F and M2-1 proteins after infection with RSV was markedly inhibited from 5 μg/ml curcumin, whereas upregulation of claudin-4 and occludin at the membranes after infection with RSV was inhibited by 10 μg/ml curcumin." (PMID 24058438, 2013).
infection (continued). "Moreover, the mRNA levels of CLDN4 at 14 days post-infection were substantially higher in the sECL2 group compared to the vehicle group." (PMID 39875947, 2025). "Moreover, in this intranasal infection model, increased mRNA levels of Cdh1 (E-cadherin), Tjp1 (ZO-1), Cldn4 (claudin 4), Cldn5 (claudin 5), and Cldn18 (claudin 18) were observed after IFN-β treatment." (PMID 36559113, 2022). "Thereby, we could conclude that while the overall CLDN-4 mRNA and protein expression in pOECs is unaltered, Ct infection does lead to a timely defined relocation of the tight junction protein CLDN-4 from the cell membrane into the Ct inclusion." (PMID 34684219, 2021). "Furthermore, Ct infection induced an accumulation of claudin-4 in the Ct inclusion with a coinciding reduction of membrane-bound claudin-4." (PMID 34684219, 2021). "To facilitate the utilization of the relevant swine model for Ct host–pathogen interactions, we characterized the developmental cycle of Ct in pOECs, the induced cellular immune response, and the effect of Ct infection on the pOEC expression of the tight junction protein CLDN-4." (PMID 34684219, 2021). "The scoring confirmed the initial observation: In the early stages of infection, at 0 and 6 hpi, CLDN-4 expression was strongest at the cell surface in both MOCK- and Ct-infected pOECs: the median CLDN-4 expression scores are ~1.8 for both, MOCK- and Ct-infected pOECs." (PMID 34684219, 2021). "We additionally use these relevant primary pOECs to demonstrate that while the overall mRNA and protein expression of CLDN-4 is unaltered (respectively), Ct infection triggers a redirection of CLDN-4 into the Ct inclusion that leads to a decrease in CLDN-4 expression on the pOEC membrane." (PMID 34684219, 2021). "In addition, in EcN + C. jejuni, the expression of the CLDN2, CLDN4, and CLDN11 encoding genes was down-regulated in comparison to infection with C. jejuni." (PMID 28878749, 2017). "In addition, in EcN + C. jejuni, the expression of the CLDN2, CLDN4, and CLDN11 encoding genes was up-regulated in comparison to infection with C. jejuni." (PMID 28878749, 2017). "We have previously prepared sublines of the human epithelial cell line 2008, designated as CLDN3KD and CLDN4KD, in which CLDN3 or CLDN4 was constitutively knocked down by infection with a lentivirus expressing an shRNAi targeting to one or the other of these two claudins." (PMID 23805314, 2013). "Our study also indicates the inner foreskin of males at risk of infection has TJ alterations such as the absence of membrane-bound claudin 4, extended membrane localization of claudin 1, and a more intense occludin staining pattern, suggestive of permeability differences." (PMID 25268493, 2014). "Our study suggests that in the later stages of infection, a higher amount of GP3 downregulates CLDN4, subsequently inhibiting IFN-β promoter activity to facilitate PRRSV infection." (PMID 39875947, 2025). "Analysis of murine colons following infection showed that mice infected with C. difficile had significantly downregulated colon tight junction proteins (TJPs; ZO-1, OCLN, and CLDN4)." (PMID 38193707, 2024). "The level of claudin-4 was markedly increased in the C. malonaticus LPS-treated group compared with the control group, which reveals that the disruption of tight junctions during infection of C. malonaticus LPS may also trigger upexpression of claudin-4 as a host’s stress response." (PMID 36211338, 2022). "Compared to mock-infected groups, Claudin 1 (CLDN1) and CLDN4 were significantly upregulated, while CLDN8 and Occludin (OCLN) were downregulated in the HP-PRRSV infection group." (PMID 35336858, 2022). "SFB promoted barrier integrity by preventing downregulation of tight junction components claudin 4 and 8 in the chronic phase of MNV infection (4 weeks post infection)." (PMID 31396223, 2019).